CTAG2 (cancer/testis antigen 2)
Synonyms: CT2; CT6.2; LAGE-1; ESO2; LAGE1; CAMEL; MGC3803; MGC138724; CT6.2a; CT6.2b; LAGE-1a; LAGE-1b; LAGE2B
Tractability: PROTAC: ubiquitination databases record sites on it.
Gene: Protein-coding gene on chromosome X (154,651,972 to 154,653,579, reverse strand). Ensembl gene ENSG00000126890.
Subcellular location (Human Protein Atlas): Vesicles; Nucleoplasm
Gene Ontology:
Molecular function: protein binding
Biological process: tRNA threonylcarbamoyladenosine metabolic process
Cellular component: centrosome
Homologues: Orthologues: rat Ctag2l1 (29% identical), rat Ctag2l2 (27% identical), mouse Ctag2l1 (27% identical), mouse Ctag2l2 (26% identical), mouse Ctag2 (23% identical), rat Ctag2 (21% identical), tropical clawed frog lage3 (17% identical), Drosophila melanogaster Tcs6 (13% identical). Paralogues in human: CTAG1A (86% identical), CTAG1B (86% identical), LAGE3 (31% identical).
Diseases named in the same sentence as CTAG2 in open-access papers:
CTAG2 is named in the same sentence as 44 diseases in open-access papers, as found by Europe PMC text mining. Sharing a sentence is not in itself a finding about the gene and the disease. The quoted sentences say what the papers report.
breast carcinoma (9 papers, 2001 to 2021). "Besides FGF13 and VEGFD, the candidate CTAG2 is involved in cellular movement and has previously been associated with invasion in breast cancer." (PMID 30555413, 2018). "CTAG2, normally only expressed in the testis, is involved in the invasive behavior of breast cancer and is highly expressed in gastrointestinal and breast carcinomas." (PMID 30555413, 2018). "Here, we find that the CTA genes SPANX-A/C/D and CTAG2 are coordinately induced in breast cancer cells and regulate distinct features of invasive behavior." (PMID 26895102, 2016). "Functionally, CTAG2 was shown to promote breast cancer cell invasion." (PMID 34988553, 2021). "Our results suggest that CTAG2 can promote the directional migration of breast cancer cells." (PMID 26895102, 2016). "Here, we find that SPANX-A/C/D, CTAG2, GAGE and PAGE2-2/B promote breast cancer cell invasion in organotypic culture, revealing that the induction of these CTAs can contribute to the acquisition of neoplastic traits." (PMID 26895102, 2016). "Through a combination of gene expression analysis and function testing, we found that the CTA genes SPANX-A/C/D, CTAG2, GAGE and PAGE-2/2B can be essential for breast cancer invasion." (PMID 26895102, 2016). "Together, these results suggest that that anomalous expression of SPANX-A/C/D, CTAG2, GAGE and PAGE-2/2B can contribute to the induction of breast cancer cell invasion." (PMID 26895102, 2016). "Of 16 CTAGs examined in the first panel of 42 breast cancer samples, seven antigens were found not to be expressed in any of the specimens: SSX2, SSX4, CTAG2, CAGE1, MAGEA1, MAGEA4 and MAGEA11." (PMID 17650306, 2007).
melanoma (8 papers, 2006 to 2022). A malignant, usually aggressive tumor composed of atypical, neoplastic melanocytes. "We found CTAG2 up-regulated in BC, but down-regulated in melanoma." (PMID 25077705, 2014).
myeloma (5 papers, 2013 to 2022). "Among the genes located on chromosome X, CTAG1, CTAG2 and MAGEB2 belong to the cancer testis gene family (CTAGs), which have been previously demonstrated to have prognostic value in patients with myeloma." (PMID 24913504, 2015).
sarcoma (4 papers, 2008 to 2022). A usually aggressive malignant neoplasm of the soft tissue or bone. "For example, PRAME, CTAG1, and CTAG2 have been reported to be over-expressed in liposarcoma compared with a variety of normal tissues, and recent studies have reported the expression of these and other CTAGs in several sarcoma subtypes." (PMID 18460215, 2008). "Importantly, SPANX-C and CTAG2 are also expressed in prostate, lung, bladder, sarcoma and melanoma cancers, suggesting that these genes may promote invasion in additional tumor types." (PMID 26895102, 2016).
esophageal (3 papers, 2015 to 2022). "Several TAAs are highly expressed in EC, among which the most common TAAs have been confirmed in EC till date, including New York esophageal squamous cell carcinoma 1 (NY-ESO-1), TTK protein kinase (TTK), cancer-testis antigen 2 (CTAG2), and melanoma-associated antigen-A (MAGE-A)." (PMID 36119033, 2022).
ovarian carcinoma (3 papers, 2013 to 2024). A malignant neoplasm originating from the surface ovarian epithelium. "Similarly, CTAG2 (alias LAGE-1, sharing 94% homology with NY-ESO-1) was expressed in 21% of epithelial ovarian cancer tissues, 30% of which also had detectable autologous antibodies." (PMID 34681879, 2021).
serous ovarian cancer (3 papers, 2021). "In the serous ovarian cancer patients of cohort 2 (n = 20/80), detectable antibodies (Z-scores > 0) were seen against CTAG2 (n = 3/20, 15%), SHARPIN (n = 2/20, 10%), PNMA2 (n = 2/20, 10%), MAGEB4 (n = 1/20, 5%), MRFAP1L1 (n = 1/20, 5%), SERPINB1 (n = 1/20, 5%) and XAGE3 (n = 1/20, 5%)." (PMID 34681879, 2021).
osteosarcoma (2 papers, 2014 to 2022). A usually aggressive malignant bone-forming mesenchymal neoplasm, predominantly affecting adolescents and young adults. "We believe that LSAMP is a tumor suppressor gene in osteosarcomas and that LSAMP suppress tumors by reducing the proliferation rate of cancer cells, possibly through upregulation of one or more of the genes HES1, CTAG2 and KLF10." (PMID 24885297, 2014).
breast tumors (1 paper, 2016). "SPANX-A/C/D, CTAG2 and GAGE have been previously identified as CTAs that are induced in breast tumors and are not detected in normal adult female tissues, including mammary epithelium." (PMID 26895102, 2016).
colorectal tumors (1 paper, 2015). "In our prior RT-PCR study, colorectal tumors were assessed for the expression of MAGE-A3 and CTAG2 by RT-PCR and the expression rates were found to be 28% and 17%, respectively." (PMID 26244168, 2015).
infantile hemangiomas (1 paper, 2013). "Our finding that CTAG2 is highly expressed in infantile hemangiomas may lead to the development of immune-mediated therapies against infantile hemangiomas." (PMID 23531100, 2013).
liposarcoma (1 paper, 2008). A usually painless malignant tumor that arises from adipose tissue. "The current results confirmed our earlier report of over-expression of PRAME, CTAG1 and CTAG2 in liposarcomas using the U_95 array with the newer U_133 array, and also demonstrated that the expression of these potential targets of immunotherapy is heterogeneous among STS." (PMID 18460215, 2008).
myxoid liposarcoma (1 paper, 2008). A liposarcoma characterized by the presence of round non-lipogenic primitive mesenchymal cells and small signet ring lipoblasts within a myxoid stoma with a branching vascular pattern. "For example, CTAG2 was expressed in ~60% of the non-myxoid liposarcoma samples, but in none of the LMS, AF, or MFH samples." (PMID 18460215, 2008).
paraganglioma (1 paper, 2017). A benign or malignant neoplasm arising from paraganglia located along the sympathetic or parasympathetic nerves. "Analysis of the expression of CTAG2 and CT45-2 in the TCGA Pheochromocytoma and Paraganglioma RNA-Seq datasest revealed that CTAG2 was expressed in 47% (89/187) of the samples." (PMID 28327598, 2017).
pituitary adenomas (1 paper, 2023). "Studies performed on lactotroph pituitary adenomas highlighted aggressive behavior, especially in the male gender, when the expression of ERα was reduced, probably associated also with the expression of genes situated on chromosome X (CTAG2, FGF13, and VEGF) that influence the ER pathway." (PMID 37958702, 2023).
round cell liposarcoma (1 paper, 2022). A poorly differentiated liposarcoma, characterized by the presence of solid sheets of primitive round mesenchymal cells and the absence of myxoid stroma. "CTAG2 (encodes cancer-testis antigen 2) and MAGEA1 were shown to be expressed consistently in myeloid and round-cell liposarcomas; hence, these genes are used as immunotherapy targets in the treatment of these cancers." (PMID 35565356, 2022).
squamous cell carcinoma (1 paper, 2019). A carcinoma arising from squamous epithelial cells. "Overexpression of CFBF, PAGE2, CALM3, DSG3, CTAG2, and FAM83C was seen only in squamous cell carcinoma." (PMID 31877723, 2019).
cancer (31 papers, 2001 to 2025). A tumor composed of atypical neoplastic, often pleomorphic cells that invade other tissues. "Higher ICI-4W expression of extracellular matrix (ECM) genes, including trypsinogens (PRSS1 and PRSS2) and matrix metalloproteases, and genes encoding cancer antigens (CTAG2, SAGE1, MAGEA1/A4/A10, POTEE, and PRAME) was significantly associated with ICI resistance and tumor growth during ICI-4W." (PMID 37433281, 2023). "T cells targeting cancer/testis antigen 2 (CTAG2) and melanoma-associated antigen 3 (MAGE-3), highly expressed on esophageal cells, play a key role in the anti-cancer immune response." (PMID 40136652, 2025). "Immuno-proteomic screening demonstrated that elevated titers of auto-antibodies to the cancer-testis antigens (CTAG2) are correlated with diverse cancer types and suggest decreased differentiation in cancer cells." (PMID 36761693, 2022). "CTAG2 (cancer-testis antigen-2) encodes for the autoimmunogenic tumor antigen, LAGE-1, expressed by cancer cells, including PCa." (PMID 34988553, 2021). "Several cancer-testis antigens, including CTAG2 and CT45-2 were also found to be less methylated in tumour tissue than in normal tissue." (PMID 28327598, 2017). "MAGEA6 and CTAG2 are expressed in testis, and in very low levels in placenta but are observed to be highly expressed in NSCLC and various cancer types." (PMID 34048178, 2021). "HES1, CTAG2 and KLF10 have all been shown to play a role in cancer biology." (PMID 24885297, 2014). "Not surprisingly, several cancer testis antigens (CTA) including CT45A1, CT45A3, CT45A5, CTAG1B and CTAG2 were highly expressed in TNB-High or TMB-High tumors." (PMID 41562064, 2025). "Indeed, transcripts for a number of antigens such as CTAG2, MAGEA3, and MAGEA6, which are normally expressed in testis and are immunogenic when aberrantly expressed in cancer tissue, were strongly expressed in a subset of IE1, but not IE2, samples." (PMID 36609566, 2023).
tumor (23 papers, 2004 to 2025). "Correlative analysis revealed that, in men, CTAG2 expression was strongly correlated with known lactotroph tumor aggressiveness markers implicated in the cell cycle (CENPE, AURKB, CCNB1, ADAMTS6)." (PMID 30555413, 2018). "However, the role of CTAG2, coding for one of several tumor-associated autoantibodies that may have the ability to allow earlier diagnosis of SOC, is in line with our results." (PMID 34283076, 2021). "CTAG2 depletion drastically reduced primary tumor growth, indicating that CTAG2 regulates additional functions related to tumor growth." (PMID 26895102, 2016). "Our results demonstrating that SPANX-A/C/D and CTAG2 were necessary for invasion suggested that these CTAs may contribute to tumor development in vivo." (PMID 26895102, 2016). "Antimetastatic RARβ2 signalling, direct or indirect, results in an elevation of expression for genes such as tumor-cell antigens (CTAG1 and CTAG2), those involved in innate immune response (e.g., RIG-I/DDX58), and tumor suppressor functions (e.g., TYRP1)." (PMID 16255778, 2005). "Thus, our discovery that SPANX-A/C/D, CTAG2, PAGE-2/2B can be necessary for invasion reveals a mechanistic contribution for these CTAs during tumor progression." (PMID 26895102, 2016). "Unlike CTAG2, SPANX-A/C/D depletion had a relatively small impact on primary tumor growth, indicating that the growth dependency observed for CTAG2 was not a general feature of CTAs expressed in SUM159T cells." (PMID 26895102, 2016).
CTAG2 also shares sentences with these, for which no sentence is quoted: lung carcinoma (3 papers); esophageal cancer (2); esophageal squamous cell carcinoma (2); hypopharyngeal carcinoma (2); leiomyosarcoma (2); peritoneal carcinoma (2); prostate carcinoma (2); Autoimmunity (1); bladder cancer (1); colon cancer (1); colorectal carcinoma (1); esophageal tumors (1); gastric carcinoma (1); hepatocellular carcinoma (1); mesothelioma (1); multiple sclerosis (1); non-small cell lung carcinoma (1); pheochromocytoma (1); rheumatic diseases (1); seminoma (1); soft tissue sarcoma (1); synovial sarcoma (1); testicular tumours (1); transitional cell carcinoma (1); urothelial carcinoma (1).